EGFR (epidermal growth factor receptor)
Diseases named in the same sentence as EGFR in open-access papers (continued):
Sharing a sentence is not in itself a finding about the gene and the disease.
cancer (continued). "Its sustained activation, triggered by the activation of epidermal growth factor receptor (EGFR), has been implicated in cell proliferation and cancer development." (PMID 38201504, 2023). "These cancer-activating mutations, which occur in the tyrosine kinase domain of the EGFR, were classified as oncogenic drivers of non-small cell lung cancer (NSCLC), one of the most lethal cancers in the world." (PMID 37754201, 2023). "The FDA-approved indication for individual EGFR-TKIs often requires the molecular profiling of tumor DNA for the presence of variants in specific cancer cell types to predict the likelihood of response or the development of drug resistance." (PMID 36734129, 2023). "EGFR gene, which encodes the EGFR tyrosine kinase, is abnormally amplified, rearranged, and mutated in a subset of cancers." (PMID 37341071, 2023). "One of the most critical diagnostic parameters evaluated in cancer tissue is the status of the estrogen receptor (ER) and epidermal growth factor receptor (EGFR)." (PMID 36982173, 2023). "The prevalence of shared EGFR mutations in multiple cancer types provides a potentially ideal resource for public neoantigens." (PMID 37766136, 2023). "The dysregulation of EGFR signaling is a common cause of tumorigenesis as it leads to aberrant cancer cell survival, invasion, and metastasis." (PMID 37495186, 2023). "MAPK3, MAPK1, and EGFR were ranked among the top 3 target proteins, and were also the key proteins tightly associated with cancer." (PMID 38143380, 2023). "Cannabinoids such as Cannabidiol (CBD), Cannabigerol (CBG), and Cannabinol (CNB) have been tested for their ability to bind to and inhibit the Epidermal Growth Factor Receptor (EGFR), which is associated with cancer progression." (PMID 37128337, 2023). "It elicits potent antitumor immunity in vitro and in vivo by expressing monoclonal antibodies specific for T-cell-associated CD3 and cancer cell-associated epidermal growth factor receptor (EGFR)." (PMID 37005658, 2023). "As a well-established protumorigenic signaling pathway, EGFR is frequently mutated in various types of cancer." (PMID 37020674, 2023). "Abnormal expression and dysregulated intracellular signaling through HER family members has a pivotal role in carcinogenesis, and hyperactivating mutations of EGFR have been identified in several cancer types." (PMID 37626832, 2023). "For pan-cancer analysis (using 56 cancer cell lines), there were 59 genetic alterations with significant association with increased daunorubucin-EGFR inhibitor synergy." (PMID 37629110, 2023). "In the search of novel radiopharmaceuticals to broaden the spectrum of diagnostic and therapeutic options in the fight against cancer, a series of 99mTc complexes directed against the Epidermal Growth Factor Receptor (EGFR) was presented." (PMID 36952073, 2023). "We found that levels of CD8+ T cells or CD4 memory activated T cells were higher in EGFR wild-type and rare variant cancers than in EGFR L858R and exon 19 deletion types." (PMID 37033978, 2023). "Although no EGFR L858R mutation was detected in the second operation's cancer tissue, EGFR L858R mutation was detected in the two largest nodules from the first operation." (PMID 36599687, 2023). "This cancer is due to EGFR mutations in ~10–15% of Caucasian patients and in up to 50% of Asian patients." (PMID 37989743, 2023). "To examine the involvement of PAI-1 in the proliferation of EGFR-mutated cancer cells with tolerance to EGFR-TKIs, we investigated the effect of PAI-1 inhibition on the proliferation of EGFR-TKI-tolerant cells." (PMID 36831438, 2023). "EGFR TKIs have a high response rate (60%–70%) in EGFR-mutated cancers, while Anaplastic Lymphoma Kinase (ALK) inhibitors have a comparable response rate (60%) in patients with ALK translocations." (PMID 38186568, 2023). "Spontaneous dimerization of EGF receptors (EGFR) and dysregulation of EGFR signaling has been associated with the development of different cancers." (PMID 37752992, 2023).
cancer (continued). "Since EGFR is frequently overexpressed and/or mutated in multiple cancer types, it has prompted the development of a number of specific targeted therapeutics." (PMID 38201251, 2023). "EGFR and other family members are overexpressed or amplified in cancer, causing uncontrolled proliferation of tumor cells." (PMID 36782251, 2023). "Cancer cells gain resistance towards these EGFR-targeted therapies, usually through acquired mutations in the tyrosine kinase domain." (PMID 38137520, 2023). "There is much evidence about the up-regulation of lipogenesis in EGFR-mutated cancer cells resistant to TKI." (PMID 38001865, 2023). "Cancer-associated fibroblast (CAFs) have been reported to stimulate AhR-dependent proliferation and EGFR-TKI resistance in NSCLCs through production and release of the tryptophane metabolite and potent AhR ligand kynurenine." (PMID 37696458, 2023). "Patients with metastatic NSCLC treated with osimertinib, harboring at least one atypical EGFR mutation, excluding concurrent deletion of exon 19, L858R, or T790M mutations, from six U.S. academic cancer centers were included." (PMID 36879929, 2023). "A recent study indicated that mice with EGFR mutations are more likely to develop cancer after exposure to pollutant particles mediated by an inflammatory protein called interleukin 1 beta, which is part of the body's immune response to PM2.5 exposure." (PMID 36975376, 2023). "Previous molecular studies found a clear association between PGRMC1 and the EGFR signalling pathway in cancer." (PMID 37887342, 2023). "Strikingly, in 98.9% (279/282) of cases, the compound EGFR mutations were located on the same allele, which also infers that they were in the same cancer cell." (PMID 36829178, 2023). "The data analysis revealed ten significant cancer types that both overexpress EGFR in comparison to normal tissues and have been thoroughly examined to allow assessments of the association between EGFR and cancer prognosis." (PMID 36768973, 2023). "EGFR gene amplification and EGFR tyrosine kinase domain mutation were shown to happen in patients with carcinoma." (PMID 37042307, 2023). "The epidermal growth factor receptor (EGFR) is frequently mutated in diverse types of carcinomas, including GC." (PMID 36260159, 2023). "The progression from preneoplastic lesions to carcinoma following K-Ras mutation requires Epidermal Growth Factor Receptor (EGFR) activity, and oncogenic K-Ras increases the level of this receptor." (PMID 36975534, 2023). "Overexpression of the EGFR gene and mutations of the EGFR tyrosine kinase domain were reported in the development and progression of different carcinomas including lung, colorectal, breast, brain, and pancreas." (PMID 37716963, 2023). "EGFR has been shown to increase in expression in the early steps of carcinoma development and is associated with poor prognosis." (PMID 37444523, 2023). "In many patients, resistance against cancer therapy arises from an acquired mutation in the EGFR kinase domain (T790M)." (PMID 35821615, 2022). "Together, these data demonstrate that hydrophilic mutations locatedin the hydrophobic region of the EGFR transmembrane domain are rarelydetected in cancer." (PMID 36148499, 2022). "EGFR gene mutations typically result in overexpression or constitutive tyrosine kinase activity, leading to enhanced cancer growth." (PMID 36010982, 2022). "Another cohort study reported that 63% of NSCLC patients showed onset of EGFR mutations and proliferation of cancer after treatment with EGFR-TKIs during re-biopsy, while a 33% frequency of T790M mutation was found." (PMID 36552956, 2022). "The MYC binding protein 2 (MYCBP2) was found to be a binding partner for the epidermal growth factor receptor (EGFR), which is frequently mutated in various cancers." (PMID 35053843, 2022). "In several cancer settings, constitutive EGFR activation has been linked to increased glucose uptake, lactate secretion and glutamine utilization." (PMID 36340043, 2022).
cancer (continued). "Genetic mutations are also capable of inducing the EGFR active state, and these mutations are common in multiple cancers." (PMID 36054194, 2022). "The mutation rate of EGFR in Chinese cancer patients is 10.6%, which is higher than that observed in the weighted U.S. pan-cancer (3.1%) estimates." (PMID 36163440, 2022). "EGFR recycling is enhanced or its degradation is weakened with gene mutations in cells, leading to abnormally high expression of EGFR, which is the main cause for the pathogenesis of various cancers." (PMID 35614042, 2022). "Erlotinib can induce apoptosis and autophagy in NSCLC cells with EGFR activating mutations, and inhibiting the autophagy process can enhance the cytotoxicity of erlotinib to cancer cells." (PMID 35600411, 2022). "Abnormal EGFR and ErbB2 activation can be observed in a wide range of mechanisms like overexpression, gene mutations, and autocrinergic stimulation in cancers." (PMID 36438839, 2022). "Aberrant activation of the epidermal growth factor receptor (EGFR) by mutations has been implicated in a variety of human cancers." (PMID 36531494, 2022). "Deregulated EGFR signaling in cancer has been linked to resistance to chemo- and/or radiotherapy as well as increased DNA damage repair capacity, whereas inhibition of the EGFR attenuates DNA damage repair." (PMID 35388101, 2022). "Novel antidiarrheal agents are needed to reduce epidermal growth factor receptor-tyrosine kinase inhibitor-associated diarrhea to improve the quality of life and treatment outcome in cancer patients." (PMID 36297833, 2022). "The efficacy of PD-1 and PD-L1 inhibitors is dependent on patient factors, like (i) gender, (ii) kinds of cancers, (iii) translocation and gene mutation (Kras, EGFR, ALK), and (iv) tumor metastases." (PMID 36363529, 2022). "The EGFR-mutated subtype displayed higher mutation rates of SFG than the EGFR-wildtype subtype in pan-cancer and in six individual cancer types (ACC, COAD, LUSC, SKCM, STAD, and UCEC)." (PMID 36684432, 2022). "SRC was also shown to align to the EGFR molecule to facilitate it’s signaling both upstream and downstream and is linked to stemness of cancer cells." (PMID 36163190, 2022). "Recent findings indicate that EGFR-mutated cancers are correlated with increased occurrence of diffuse lung metastases." (PMID 35954442, 2022). "Studies have shown that EGFR kinase domain mutations are happened in cancer cells, which induces ligand-independent phosphorylation and activates the downstream uncontrolled signal transmission." (PMID 36545470, 2022). "Due to the mutation-mediated destabilization of the EGFR TK domain, abnormal activation of EGFR constitutively propagates EGFR TK activity and downstream pro-oncogenic signaling pathways to drive cancer cell survival and proliferation." (PMID 34319535, 2022). "Irregularities in the signaling pathway lead to malfunctioning of the EGFR, and various studies have revealed the determining cause of cancer and most of the results correlate to the overexpression of EGFR." (PMID 35769445, 2022). "The expression of epidermal growth factor receptor (EGFR) in cancer is often associated with a more aggressive phenotype and predictive of poor prognosis." (PMID 35252204, 2022). "EGFR activation is linked with proliferation, metastasis, apoptosis inhibition, and radio-chemotherapy resistance in cancer." (PMID 35402265, 2022). "A compound mutation refers to the simultaneous detection of two or more different types of EGFR mutations in patient cancer cells." (PMID 35840984, 2022). "These mutations are associated with the clonal evolution of drug-resistant cancer cells in patients treated with anti-EGFR antibodies." (PMID 35323316, 2022). "In this study, we aimed to (i) propose an efficient CTC isolation protocol for precise EGFR mutation testing; and then (ii) compare the mutational analysis between cancer tissues and CTCs." (PMID 36142574, 2022).
cancer (continued). "Target genes of the top 10 miRNAs were associated with cancer, prolactin pathway, EGFR, ErbB, and FoxO signaling pathway." (PMID 36313069, 2022). "Most targeted cancer therapies are targeting specific somatic mutations, such as EGFR, BRAF, VEGF and BRCA mutations in various cancers." (PMID 36457740, 2022). "We aimed to determine the biological effects of CD148 Q276P/R326Q mutations in cancer cell proliferation and growth factor signaling, with emphasis on EGFR signaling." (PMID 34791835, 2022). "Consistent with the low number of average mutations per sample, we find that the EGFR-mut cancers conserved 16 genes related to DNA repair (e.g., BRCA1 and BRCA2)." (PMID 36612014, 2022). "Of 92 cancers with EGFR L858R or exon 19 deletion mutation detected by OncoPanel, 49 had mutations identified by ddPCR in plasma specimens." (PMID 35202431, 2022). "Accordingly, the overexpression or gain-of-function mutations of EGFR are reported in different types of aggressive and chemoresistant cancers." (PMID 35814444, 2022). "Studies have shown the correlation between EGFR mutation and different cancers, which activate the cell surface receptor." (PMID 35463723, 2022). "The generated mutation in EGFR led to the acquired drug resistance and reduced efficacy in cancer treatment." (PMID 35821615, 2022). "Regarding anti-cancer treatment, only a few patients carrying EGFR mutations had received TKI-based therapy." (PMID 36011410, 2022). "Collectively, EGFR-TKI plus α-PD-1/PD-L1 therapy would maximize the efficacy of immunotherapy in patients with EGFR-mutated cancers." (PMID 35062949, 2022). "During treatment with cetuximab, cancer cells acquire genetic alterations such as gain-of-function mutations in EGFR and KRAS, resulting in treatment resistance." (PMID 36012427, 2022). "Anti-EGFR monoclonal antibodies are ineffective in CRC patients with a KRAS mutation due to cancer’s genetic heterogeneity." (PMID 36005485, 2022). "A clinical challenge for physicians treating patients with EGFR-mutant cancers is to appropriately identify and match patient mutations with the best EGFR TKIs." (PMID 35984165, 2022). "Taking lessons from NSCLC, we also discuss potential new treatment options for ISP-associated SNSCC harbouring EGFR Ex20ins in the context of targeted therapies, drug resistance and precision cancer medicine." (PMID 35053553, 2022). "To evaluate the concordance between EGFR mutations in cancer tissue and CTC samples, we separately analyzed the samples (n = 28) before systemic therapy from those during therapy (n = 52, 3rd month after treatment initiation)." (PMID 36142574, 2022). "KRAS G13 mutations have also been identified in cancers and have been potential therapeutic targets for epidermal growth factor receptor (EGFR) inhibitors." (PMID 36497424, 2022). "More recently, it has been shown that exosomal transference of wild-type EGFR to EGFR-mutated sensitive cancer cells promotes resistance to the mutant-selective EGFR inhibitor osimertinib by activating the MAPK and PI3K/AKT signaling pathways." (PMID 36176765, 2022). "For these patients, the EGFR-mutation occurs in essentially all of the cancer cells of the primary and metastatic tumors." (PMID 35061724, 2022). "WES showed relevant mutations in several cancer-related genes, and the comparative mRNA expression analysis showed 36 differentially expressed genes associated with EGFR tyrosine kinase inhibitors resistance, RAS, MAPK, and mTOR signaling." (PMID 35011716, 2022). "The reduction of growth in cancer cell invasion, and metastasis has been associated to EGFR downregulation." (PMID 35530318, 2022).
cancer (continued). "The antibody efficiently inhibits the EGFR associated signal transduction, prevents proliferation, arrests the cell cycle in the G1 phase and decreases interleukin 6 (IL-6) secretion by the cancer cells." (PMID 35937253, 2022). "The EGFR is a validated target in cancer therapy as elevated expression is associated with various cancer types." (PMID 35624572, 2022). "Uncommon EGFR mutations are a group of heterogeneous remainders in exon 18 to 21 that comprise approximately 20% mutations of cancer-related EGFR mutations." (PMID 35494059, 2022). "Overall, the PFHnD-Ab have the potential to expand ultrasound as a cancer diagnostic tool by selectively binding to EGFR-overexpressing cancer cells for sensitive tumor detection." (PMID 35808089, 2022). "For example, cancer neoantigens contain mutations that are specific to cancer (e.g., mutations in EGFR)." (PMID 35328459, 2022). "Epidermal growth factor receptor is frequently mutated and/or overexpressed across different cancers and is the primary target for diverse cancer treatment strategies currently adopted in clinical practice." (PMID 35157848, 2022). "The EGFR mutations in the protein kinase-like domain, namely E709K, V774M, and L861Q, were predicted to be damaging, deleterious, and cancer-related." (PMID 35977996, 2022). "To further investigate the potential connections between mixed-lineage cancer cells and EGFR mutation, we partitioned TCGA samples into two clusters based on EGFR mutation, EGFRWT and EGFRMut." (PMID 35962452, 2022). "There is new evidence that the combination of MET inhibitors with EGFR inhibitors is a promising therapeutic combination for the treatment of cancer caused by EGFR mutations in early and resistant stages of NSCLC." (PMID 36313314, 2022). "The diversity and complexity of molecular mechanisms underlying the acquired adaptation of cancer cells to targeted therapies, such as EGFR-TKIs, is an area of active investigation." (PMID 36059009, 2022). "This makes EGFR mutations highly susceptible to be exploited by cancer cells to alter their physiology and achieve immortalisation." (PMID 35158954, 2022). "Cancer cells harboring EGFR and downstream effector mutations in the signaling can be selected by EGF withdrawal." (PMID 36207749, 2022). "A multicenter phase II clinical trial from the Korean Cancer Research Group (LU17–19) aimed to evaluate the efficacy of osimertinib in NSCLC patients with EGFR ex20ins mutations after standard chemotherapy failed." (PMID 35418149, 2022). "EGFR is identified as the first one to be associated with cancer development among all receptor tyrosine kinases." (PMID 35291911, 2022). "Dysregulated EGFR signaling has long been established to be associated with cancer but our previous studies have also highlighted its importance in cardiovascular pathology." (PMID 36559167, 2022). "Cancer cells with EGFR mutations become dependent on EGFR for survival, making EGFR an attractive target for anticancer therapy." (PMID 36341333, 2022). "Although EMT has been extensively studied in the context of cancer, the role of exosomes secreted by EGFR-mutated tumors in the process of EMT, partial EMT and collective migration remains under-investigated." (PMID 35954442, 2022). "Apart from being conjugated with anti-B7-H3 antibody, ICG can also be conjugated with antiepidermal growth factor receptor (EGFR) monoclonal antibody (Pan) for targeting cancer-associated EGFR." (PMID 36451698, 2022).